HABP2 (hyaluronan binding protein 2)
Description:
Cleaves the alpha-chain at multiple sites and the beta-chain between 'Lys-53' and 'Lys-54' but not the gamma-chain of fibrinogen and therefore does not initiate the formation of the fibrin clot and does not cause the fibrinolysis directly. It does not cleave (activate) prothrombin and plasminogen but converts the inactive single chain urinary plasminogen activator (pro-urokinase) to the active two chain form. Activates coagulation factor VII (Probable). May function as a tumor suppressor negatively regulating cell proliferation and cell migration.
Synonyms: FSAP; PHBP; PHBSP; HGFAL; HABP; NMTC5
Tractability: Small molecule: it belongs to a druggable protein family. Antibody: UniProt places it where antibodies can reach, with high confidence; UniProt predicts a signal peptide or a membrane-spanning region; its Gene Ontology location is reachable by antibodies, with medium confidence. PROTAC: its protein half-life has been measured.
Target class: Enzyme; Hydrolase
Gene: Protein-coding gene on chromosome 10 (113,550,837 to 113,589,892, forward strand). Ensembl gene ENSG00000148702.
Subcellular location: Secreted
Gene Ontology:
Molecular function: peptidase activity; glycosaminoglycan binding; serine-type endopeptidase activity; calcium ion binding
Biological process: proteolysis; cell adhesion
Cellular component: extracellular region
Genetic constraint (gnomAD): Loss-of-function variants: 38 observed, 35.24 expected, observed/expected ratio (o/e) 1.08, 90% interval 0.83 to 1.41. The upper end of that interval is the gene's LOEUF score, 1.41, which puts it in group 5 of 6, group 1 being the genes least tolerant of losing a copy. Missense variants: 428 observed, 407.68 expected, observed/expected ratio (o/e) 1.05, 90% interval 0.97 to 1.14. Synonymous variants: 165 observed, 157.3 expected, observed/expected ratio (o/e) 1.05, 90% interval 0.92 to 1.19.
Homologues: Orthologues: chimpanzee HABP2 (99% identical), macaque HABP2 (97% identical), dog HABP2 (83% identical), pig HABP2 (82% identical), rabbit HABP2 (81% identical), mouse Habp2 (78% identical), rat Habp2 (72% identical), guinea pig HABP2 (70% identical), Drosophila melanogaster CG30289 (16% identical), Drosophila melanogaster CG30414 (16% identical), Drosophila melanogaster CG30287 (14% identical), Drosophila melanogaster CG14780 (14% identical), and 7 more. Paralogues in human: HGF (24% identical), MST1 (24% identical), GZMA (17% identical), GZMK (17% identical), PIK3IP1 (10% identical).
Diseases named in the same sentence as HABP2 in open-access papers:
HABP2 is named in the same sentence as 67 diseases in open-access papers, as found by Europe PMC text mining. Sharing a sentence is not in itself a finding about the gene and the disease. The quoted sentences say what the papers report.
Stroke (7 papers, 2016 to 2025). Sudden impairment of blood flow to a part of the brain due to occlusion or rupture of an artery to the brain. "The results showed that after adjusting for covariates, high-risk interaction genotypes in HABP2 rs7923349 and HABP2 rs932650 were independently associated with higher stroke risk (OR, 3.578, 95% CI: 2.618–4.890, p < 0.001)." (PMID 39974357, 2025). "Previous studies showed that a variant in HABP2 was associated with the risk of atherosclerosis, venous thromboembolic disease, and stroke." (PMID 38827573, 2024). "This study detects that HABP2 rs7923349 SNPs are related to carotid stenosis and moderate to severe carotid stenosis in people who are in high risk for stroke." (PMID 36686520, 2022). "Moreover, GMDR analysis showed significant gene–gene interactions between HABP2 rs7923349, HABP2 rs932650, and high-risk interaction genotypes between these two variants were independently associated with higher stroke risk." (PMID 39974357, 2025). "A variant in the HABP2 gene is a genetic susceptibility locus to stroke." (PMID 38827573, 2024). "HABP2, which encodes for an extracellular serine protease involved in coagulation, fibrinolysis, and inflammation, was identified through a young-onset stroke GWAS where only stroke cases with age <60 years were studied, and replicated in an independent dataset [40•]." (PMID 27796860, 2016). "HABP2, which encodes an extracellular serine protease involved in coagulation, fibrinolysis and inflammatory pathways, may be a genetic susceptibility locus in early-onset stroke." (PMID 36686520, 2022). "In this study, we identified the associations of variants in HABP2 rs7923349, HABP2 rs932650, NOS2A rs8081248 with stroke." (PMID 39974357, 2025). "In the present study, we found a high prevalence of carotid atherosclerosis in the high-risk stroke population in China and also identified the associations of variants in IL1A rs1609682, PPARA rs4253655, and HABP2 rs7923349 with carotid atherosclerosis." (PMID 37292135, 2023). "Two other recent studies have also described associations of variants near HABP2 and AQP9 to be associated with all ischemic stroke and all stroke, respectively [40•, 41•]." (PMID 27796860, 2016). "HABP2 rs7923349, NOS2A rs8081248, HABP2 rs932650 were related to stroke in univariate analysis." (PMID 39974357, 2025).
thyroid cancer (5 papers, 2016 to 2024). "Furthermore, PHBP mRNA levels were found to be upregulated in non-small-cell lung cancer (NSCLC), while a downregulation and loss of function mutation of HABP2 were seen in head and neck squamous cell carcinoma and thyroid carcinoma, separately." (PMID 38791985, 2024). "Data are available in several publicly accessible databases that could have also been used to interrogate the potential biological relevance of HABP2 expression in thyroid cancer." (PMID 28884020, 2017).
breast cancer (4 papers, 2015 to 2020). A primary or metastatic malignant neoplasm involving the breast. "In this study, we identified three novel MD loci at genome-wide significance (percent dense volume [HABP2] and absolute dense volume [INHBB, LINC01483]), of which two (HABP2, LINC01483) represent putative novel breast cancer susceptibility variants." (PMID 29665850, 2018). "In summary, we report three novel MD loci at genome-wide significance, of which HABP2 and LINC01483 may represent putative new breast cancer susceptibility loci." (PMID 29665850, 2018). "Of the newly identified loci, two (HABP2 and LINC01483) showed associations with MD that are consistent with the MD-breast cancer risk association, suggesting that part of their effect on breast cancer susceptibility is mediated through a directionally consistent change in MD." (PMID 29665850, 2018). "In conclusion, no co-segregation of the HABP2 p.G534E was found in three families with NMTC and breast cancer." (PMID 28402931, 2017).
ischemic stroke (4 papers, 2016 to 2025). A stroke disorder caused by obstruction of blood flow to the brain, due to thrombotic (local blood clot formation) or embolic (due to a blood clot or other material traveling from another site) event. "There was an obvious gene–gene interaction observed in HABP2 rs7923349, HABP2 rs932650, the high-risk interaction genotype between the two variants is an independent risk factor for ischemic stroke." (PMID 39974357, 2025). "The high-risk interactive genotypes among HABP2 rs7923349, HABP2 rs932650 distinctly increased the risk of ischemic stroke." (PMID 39974357, 2025). "Three genes involved in inflammation and endothelial function were associated with ischemic stroke (HABP2 rs7923349, NOS2A rs8081248, HABP2 rs932650)." (PMID 39974357, 2025). "In addition, we used multivariate logistic regression to evaluate the risk of ischemic stroke associated with high-risk interaction genotypes between HABP2 rs7923349 and HABP2 rs932650." (PMID 39974357, 2025). "Furthermore, we found a significant gene–gene interaction among ITGA2 rs1991013, IL1A rs1609682, and HABP2 rs7923349, and the high-risk interactive genotypes in the three SNPs independently increased ischemic stroke and other vascular events." (PMID 38827573, 2024). "Furthermore, we identified the specific SNPs and interaction among IL1A rs1609682, ITGA2 rs1991013, and HABP2 rs7923349 in genes involved in inflammation and endothelial function increased the risk of carotid atherosclerosis, ischemic stroke, and composite vascular events." (PMID 38827573, 2024). "In single SNP analysis, we found that two endothelial function related gene variants (HABP2 rs7923349, HABP2 rs932650) and one inflammation related gene variant (NOS2A rs8081248) were significantly associated with ischemic stroke." (PMID 39974357, 2025). "Fourth, although we found that the high-risk interactive genotypes in ITGA2 rs1991013, IL1A rs1609682, and HABP2 rs7923349 independently increased ischemic stroke and other vascular events, the detailed molecular mechanisms remain unclear." (PMID 38827573, 2024). "In the context of ischemic stroke, peripheral blood-derived exosomes containing hyaluronan-binding protein 2 (HABP2) promote the expression of protease-activated receptors 1 (PAR1) in astrocytes causing activation of the phosphoinositide 3-kinase (PI3K) / AKT / mTOR pathway." (PMID 39652154, 2024).
lung adenocarcinoma (4 papers, 2015 to 2024). A carcinoma that arises from the lung and is characterized by the presence of malignant glandular epithelial cells. "HABP2 gene overexpression has been observed in lung adenocarcinoma and has been proposed as a novel biomarker for the same." (PMID 39484215, 2024). "To test the functional significance of HABP2 upregulation, we generated stable vector control and HABP2 overexpressing human SK-LU-1 lung adenocarcinoma cells." (PMID 26258071, 2015). "We next examined HA- and HABP2-regulated SK-LU-1 human lung adenocarcinoma cell motion and migration." (PMID 26258071, 2015). "In vivo, overexpression of HABP2 in human lung adenocarcinoma cells increased primary tumor growth rates in nude mice by ~2-fold and lung metastasis by ~10-fold compared to vector control cells (n = 5/condition)." (PMID 26258071, 2015). "Stable control, shRNA, and HABP2 overexpressing human lung adenocarcinoma cells were evaluated using immunoblot analysis, migration, extravasation, and urokinase plasminogen activator (uPA) activation assays with or without high-molecular weight HA or low-molecular weight HA (LMW-HA)." (PMID 26258071, 2015). "Further, HABP2 overexpression increased LMW-HA-induced uPA activation, migration, and extravasation in human lung adenocarcinoma cells." (PMID 26258071, 2015).
papillary thyroid cancers (4 papers, 2016 to 2021). "We analyzed the incidence of the c.1601G>A variant of HABP2 in a Polish population consisting of 326 cases of papillary thyroid carcinoma and 400 control individuals by DNA genotyping, performed by Sanger sequencing." (PMID 28938557, 2017). "The p.G534E (c.1601G>A) variant of HABP2 was recently reported as a risk factor for familial non-medullary thyroid cancer, including papillary thyroid carcinoma." (PMID 28938557, 2017). "We found that HABP2 was not expressed in >300 of the 505 thyroid tumors included in the TCGA data set and was expressed at only low to moderate levels in the remaining tumors, indicating that HABP2 overexpression is not a common feature of papillary thyroid cancer." (PMID 28884020, 2017).
venous thromboembolism (4 papers, 2016 to 2025). Occlusion of the lumen of a vein by a thrombus that has migrated from a distal site via the blood stream. "Other associations have been reported for the G534E variant of HABP2 including thrombophilia, carotid stenosis and venous thromboembolism, but neither the proband nor her son (who also carries this variant) have hematological or vascular disorders." (PMID 27530615, 2016). "HABP2 is associated with non-medullary thyroid cancer (OMIM #616535) and susceptibility to venous thromboembolism (OMIM #188050) in an autosomal dominant fashion." (PMID 40259928, 2025).
atherosclerosis (3 papers, 2015 to 2024). A disease characterized by the build-up of fatty material and calcium deposition in the arterial wall resulting in partial or complete occlusion of the arterial lumen. "Hyaluronan binding protein 2 has been implicated in several disease processes, including atherosclerosis, ALI/ARDS, deep venous thrombosis, and cancer." (PMID 26258071, 2015). "HABP2 has been implicated in several disease processes including atherosclerosis and deep venous thrombosis." (PMID 26258071, 2015). "Hyaluronic acid binding protein 2 (HABP2) is associated with a variety of disease processes, including atherosclerosis, deep venous thrombosis, and inflammation." (PMID 36916913, 2023).
carotid atherosclerosis (3 papers, 2023 to 2024). A thickening and loss of elasticity of the walls of carotid arteries that occur with formation of atherosclerotic plaques. "There was a significant gene–gene interaction observed in IL1A rs1609682, ITGA2 rs1991013, and HABP2 rs7923349, the high-risk interactive genotypes in the three variants served as independent risk factors of carotid atherosclerosis." (PMID 37292135, 2023). "Multivariate logistic regression revealed that IL1A rs1609682 TT and HABP2 rs7923349 TT served as independent risk factors for carotid atherosclerosis (OR, 1.45, 95% CI: 1.034–2.032, p = 0.031, and OR, 1.829, 95% CI: 1.228–2.723, p = 0.003)." (PMID 37292135, 2023). "The high-risk interactive genotypes among IL1A rs1609682, ITGA2 rs1991013, and HABP2 rs7923349 significantly increased the risk of carotid atherosclerosis." (PMID 37292135, 2023). "The results exhibited that the high-risk interactive genotypes in IL1A rs1609682, ITGA2 rs1991013, and HABP2 rs7923349 were independently associated with a higher risk for carotid atherosclerosis after adjusting covariates (OR, 2.08, 95% CI: 1.257–5.980, P < 0.001)." (PMID 37292135, 2023). "Here, we found that HABP2 rs7923349 was also associated with carotid atherosclerosis." (PMID 37292135, 2023). "Furthermore, multivariate logistic regression was employed to evaluate the risk of carotid atherosclerosis conferred by the high-risk interactive genotypes among IL1A rs1609682, HABP2 rs7923349, and ITGA2 rs1991013." (PMID 37292135, 2023). "In addition, although we found that the high-risk interactions among IL1A rs1609682, ITGA2 rs1991013 and HABP2 rs7923349 increased the risk of carotid atherosclerosis, the detailed molecular mechanisms were not investigated." (PMID 37292135, 2023). "Univariate analyses revealed there were significant differences in genotype distribution of PPARA rs4253655, IL1A rs1609682, and HABP2 rs7923349 between subjects with and without carotid atherosclerosis (p < 0.05)." (PMID 38827573, 2024). "Moreover, univariate analyses showed that there were significant differences in genotype distributions of IL1A rs1609682, PPARA rs4253655, and HABP2 rs7923349 between individuals with and without carotid atherosclerosis (p < 0.05)." (PMID 37292135, 2023).
COVID-19 (3 papers, 2021 to 2024). A disease caused by infection with severe acute respiratory syndrome coronavirus 2. "The binding of hyaluronan to its receptor HABP2 mediates the abnormal thrombosis, which may cause the anosmia in COVID-19." (PMID 35593963, 2022). "Notably, HABP2, a receptor of hyaluronan is involved in blood coagulation, which may also play a key role in the dysfunction of the coagulation system in response to the increased hyaluronan level in COVID-19 patients." (PMID 35593963, 2022).
thyroid (3 papers, 2017 to 2024). "Decreasing wild-type HABP2 expression through siRNA in two thyroid cell lines and HEK293 cells increased colony formation and cellular migration, while stable overexpression in the cell lines reduced colony formation and cellular migration." (PMID 28884020, 2017). "HABP2 rs7080536 is not present in the 1000 genomes Japanese population, suggesting a low population allele frequency (AF) despite a potentially high rate of occult thyroid disease." (PMID 28884020, 2017).
E. coli infection (2 papers, 2025). "To determine the effect of PGD2 on the damage caused by E. coli infection in BMDMs and bovine endometrial tissues, we measured the expression of DAMPs (HMGB-1, HABP-2) using qPCR and immunofluorescence." (PMID 40874199, 2025). "To examine the impact of inhibiting the PGE2-EP4 axis on DAMPs expression during E. coli infection, we assessed the mRNA expression of HMGB-1 and HABP-2 in BMDM." (PMID 40666730, 2025). "The results showed that E. coli infection significantly upregulated the expression of both HMGB-1 and HABP-2 compared to the control group." (PMID 40666730, 2025). "Compared to the E. coli infection group, PGD2 significantly increased HMGB-1 and HABP-2 mRNA expression levels in BMDMs (P < 0.05)." (PMID 40874199, 2025). "To investigate the effect of inhibiting the mPGES-1–PGE2 axis on the expression of DAMPs during E. coli infection, we measured the mRNA levels of key DAMPs, such as HMGB-1 and HABP-2, in BMDM following treatment with mPGES-1 inhibitors (MF63 and MK886)." (PMID 40666730, 2025). "E. coli infection significantly increased the expression of both HMGB-1 and HABP-2 in BMDM." (PMID 40666730, 2025).
liver fibrosis (2 papers, 2019 to 2024). "In addition, single nucleotide polymorphisms in HABP2, the gene encoding FSAP, resulted in decreased FSAP enzymatic activity and is associated with the severity of liver fibrosis in patients, probably due to decreased FSAP-mediated degradation of PDGF-βa potent HSC mitogen." (PMID 31718044, 2019). "The role of PLG and HABP2 in liver fibrosis enhancement is acknowledged, while its cardiovascular effects remain uncertain." (PMID 38523778, 2024).